QNG1 (Q-nucleotide N-glycosylase 1)
Description:
Catalyzes the hydrolysis of queuosine 5'-phosphate, releasing the nucleobase queuine (q). Is required for salvage of queuine from exogenous queuosine (Q) that is imported and then converted to queuosine 5'-phosphate intracellularly. In vitro, can also catalyze the release of the q base directly from Q as substrate; however, it was shown that Q is not the biologically relevant substrate. Shows a very low activity on queuosine 3',5'-diphosphate, and cannot release q from queuosine 3'-phosphate and from the 5'-nucleotides AMP, UMP, CMP or GMP, indicating specificity for the queuine base. Can complement the yeast mutant SPAC589.05c, restoring Q incorporation into tRNA.
Synonyms: C9orf64; MGC10999
Tractability: Small molecule: a structure with a bound ligand is known. PROTAC: ubiquitination databases record sites on it.
Gene: Protein-coding gene on chromosome 9 (83,938,311 to 83,956,986, reverse strand). Ensembl gene ENSG00000165118.
Subcellular location (Human Protein Atlas): Golgi apparatus
Pathways (Reactome):
Metabolism of RNA: tRNA modification in the nucleus and cytosol
Gene Ontology:
Molecular function: protein binding; queuosine nucleosidase activity; hydrolase activity
Biological process: nucleoside salvage; tRNA queuosine(34) biosynthetic process from salvaged queuosine or its precursors; purine nucleobase salvage; tRNA modification
Cellular component: cytosol
Genetic constraint (gnomAD): Loss-of-function variants: 24 observed, 30.15 expected, observed/expected ratio (o/e) 0.8, 90% interval 0.58 to 1.12. The upper end of that interval is the gene's LOEUF score, 1.12, which puts it in group 4 of 6, group 1 being the genes least tolerant of losing a copy. Missense variants: 408 observed, 442.99 expected, observed/expected ratio (o/e) 0.92, 90% interval 0.85 to 1. Synonymous variants: 146 observed, 171.94 expected, observed/expected ratio (o/e) 0.85, 90% interval 0.74 to 0.97.
Homologues: Orthologues: chimpanzee QNG1 (99% identical), macaque QNG1 (98% identical), pig QNG1 (89% identical), dog QNG1 (87% identical), rabbit QNG1 (87% identical), guinea pig QNG1 (83% identical), rat Qng1 (77% identical), mouse Qng1 (77% identical), tropical clawed frog qng1 (63% identical), zebrafish qng1 (51% identical), Caenorhabditis elegans C11D2.4 (46% identical), Drosophila melanogaster CG9752 (43% identical).
Diseases named in the same sentence as QNG1 in open-access papers:
QNG1 is named in the same sentence as 4 diseases in open-access papers, as found by Europe PMC text mining. Sharing a sentence is not in itself a finding about the gene and the disease.
QNG1 shares sentences with these, for which no sentence is quoted: glioma (3 papers); cancer (2); lung disease (1); ovarian carcinoma (1).